VWF (von Willebrand factor)
Diseases named in the same sentence as VWF in open-access papers (continued):
Sharing a sentence is not in itself a finding about the gene and the disease.
tumor (continued). "By modulating the interaction between cancer cells and subendothelial cells, VWF seems to reduce sustained adherence of tumour cells in the microvasculature at the target organ, thus inhibiting metastatic spread." (PMID 25846632, 2015). "What is more important, immunohistochemical analysis of xenograft tumor sections for endothelial markers, including VWF and CD34, revealed that tumor angiogenesis was less in HT-29 CASP3DN cell xenograft than in parental HT-29 cell xenograft." (PMID 26431328, 2015). "While the results from the present study are in agreement with these previous findings the precise functional mechanism of vWF in tumorigenesis and tumor progression remain far from being completely understood." (PMID 25886574, 2015). "Secondary endpoints included surgical bleeding, plasma levels of vWF, and circulating tumor cells (CTCs) as measured by quantitative PCR of cytokeratin-19 transcripts." (PMID 26306290, 2015). "Tumors from the two populations were then stained for von Willebrand factor (vWF) to assess tumor vascularization and Ki67 to measure cell proliferation." (PMID 25595903, 2015). "vWF immunostaining was highest around the tumor nests, where microvessel density (MVD) was highest as well." (PMID 25886574, 2015). "In the patients with GC, the level of vWF expression was significantly higher in the tumor tissues than in the adjacent normal tissues, at both the mRNA and protein levels." (PMID 25886574, 2015). "TMPRSS2-ERG was found to associate with these factors in a manner predicting a poor outcome of the patient (high tumor stromal expression of PDGFRβ, hyaluronan, von Willebrand factor and low stromal expression of Caveolin-1)." (PMID 24505269, 2014). "PNS treatment led to decreased expression of CD34 and vWF in tumor and increased expression of these vascular markers in heart." (PMID 24903055, 2014). "A regular EC, where the GFP in tumor cells is completely distinct from vWF, only expressed the endothelial antigens." (PMID 24722469, 2014). "To investigate the tumor vasculature, we carried out immunofluorescence by confocal microscopy using the endothelial antigens vWF, CD31, and CD34 as markers." (PMID 24722469, 2014). "Consistently with the result from CD34 expression analysis, a significant decrease in the expression of vWF was observed in the tumor sections of PNS-treated complex mice compared to that from the vehicle-treated complex mice." (PMID 24903055, 2014). "Blood vessel area within tumor sections was determined by quantification of anti-vWF immunostaining using IPLab (Scanalytics, Inc.), as we have described, then compared across sample groups with α3 staining scores ranging from 0 to 3 (one-way ANOVA)." (PMID 24950714, 2014). "Quantification of tumor vessels using the vascular marker vWF revealed that the area fraction of vascular elements was significantly higher in the angiogenic phenotype compared to its non-angiogenic counterpart." (PMID 23429996, 2013). "Exposure to tumor-derived angiogenic factors promoted the expression of VE-cadherin and vWF, both of which are endothelial-specific markers, in a subset of cultured CD34+ cells (24 ± 8% and 23 ± 10%, respectively)." (PMID 24341512, 2013). "VWF has been shown to control smooth muscle cell proliferation, vascular inflammation, cell death and tumour metastasis (rev in51)." (PMID 24106610, 2013). "With regard to the effect of VWF on tumor cell death, the importance of multimer size is yet unclear." (PMID 23936617, 2013). "Secondly, it points the way to investigating the role of VWF in normal development and healing but also in pathological processes such as tumour growth, all of which depend on angiogenesis." (PMID 24106610, 2013). "Immunohistochemically, the tumor cells are reported to be positive for Von-Willebrand factor, CD31, CD34, and vascular endothelial growth factor receptor-3 (VEGFR-3)." (PMID 23607024, 2013).
tumor (continued). "The effects of VWF on angiogenesis, smooth muscle cell proliferation and tumor cell death have usually been investigated in vitro under static conditions." (PMID 23936617, 2013). "The reduction in NG2 positive microvasculature was similar to the reduction in vWF positive vessels in the NG2 shRNA treated tumours." (PMID 21829586, 2011). "The use of vWF as a marker for tumor endothelium, as is employed in, for example, fluorescent double-labeling strategies, hence can have important drawbacks." (PMID 22235379, 2011). "Serum levels of the IL-6 responsive acute phase reactants fibrinogen, haptoglobin and Von Willebrand Factor were also markedly induced in response to the tumor." (PMID 21799891, 2011). "It is known that platelet-tumor interaction through vWF facilitates extravasation through the blood vessels and results in greater metastases." (PMID 21853032, 2011). "One important finding is that vWF expression showed a remarkable heterogeneity throughout the tumor vasculature." (PMID 22235379, 2011). "Desmin and VWF double staining commonly showed co-localisation to blood vessel walls in the tumor tissue and in the normal mucosa from some stage III and IV tumors, but not from early stage tumors." (PMID 22141345, 2011). "The effects on tumor growth were accompanied by a parallel reduction in tumor cell proliferation (Ki 67) and tumorvascularization (Von Willebrand factor)." (PMID 27713352, 2010). "Reactions were normalized to vWF in order to account for the increased vascularity of the tumor specimens." (PMID 19948061, 2009). "The transcripts of murine CD31, CD34, CD45 and VWF were also detected in some tumors with variable levels, suggesting that host endothelial progenitors were involved in tumor angiogenesis to some extent." (PMID 18286204, 2008). "A dramatic decrease in tumor vasculature was observed with M867 and radiation using von Willebrand factor staining." (PMID 18509530, 2008). "As expected, the phenotype and function (VWF expression) of tumor endothelial cells in these cancers were essentially abnormal." (PMID 18286204, 2008). "All tumors were stained with vWF and microvessels were counted as a measure of tumor's angiogenic activity." (PMID 18366728, 2008). "In the first set of tumours (collected at the end of treatment period), the intensity of vWF staining was slightly reduced by each agent given alone, and markedly diminished by the double or triple combination (P<0.0001 for triple association vs control)." (PMID 17592499, 2007). "Immunohistochemically the tumor cells are positive for Von-Willebrand factor, CD31, CD34 and vascular endothelial growth factor receptor-3 (VEGFR-3)." (PMID 16859564, 2006). "Multiple studies have shown that VWF promotes adhesion among tumor cells by mediating interactions with surface molecules, enhancing their motility, invasiveness, and ability to degrade the extracellular matrix, ultimately facilitating tumor metastasis." (PMID 39901877, 2025). "Von Willebrand Factor (VWF) released by endothelial cells within the tumor vascular system activates platelets, which in turn secrete various angiogenic regulatory factors, including VEGF, epidermal growth factor (EGF), angiopoietin-1, and several anti-angiogenic cytokines." (PMID 39852571, 2025). "For example, the downregulated expression of VWF in tumor tissues is related to ERS model genes, which implies that it may have a potential essential function in cancer progression." (PMID 40729372, 2025). "Understanding the relationship between VWF and ADAMTS13 in HCC could provide valuable insights into the mechanisms underlying tumor development and progression." (PMID 40699668, 2025). "According to the results of this analysis, the median VWF was the highest in tumor tissue." (PMID 40699668, 2025). "The siRNA assay verified that VWF promotes hypoxic metabolism and might involve in the formation of an immunosuppressive tumor microenvironment." (PMID 39901877, 2025).
tumor (continued). "Additionally, we discovered that FOXC1 is a transcription factor for VWF which was found significant in promoting tumor growth and angiogenesis." (PMID 39906820, 2025). "High vWF:Ag levels correlate with larger tumor burden, advanced fibrosis, and portal hypertension." (PMID 41228207, 2025). "Similarly, von Willebrand factor (vWF) is markedly elevated in HCC, reflecting endothelial activation and tumor-associated hypercoagulability." (PMID 41228207, 2025). "Non-tumor components included endothelial cells (expressing VWF, CDH5, ECSCR, SLCO2A1, and MYCT1), pericytes (marked by RGS5, MCAM, and PDGFRB), normal oligodendrocytes (showing PTGDS, MBP, TF, and MOG expression), and TAMs (identified by CD14, AIF1, FCER1G, FCGR3A, TYROBP, and CSF1R)." (PMID 41394801, 2025). "Modulating VWF expression may enhance tumor suppression, and addressing the imbalance between VWF and ADAMTS13 may reduce angiogenesis and metastasis." (PMID 40699668, 2025). "However, our NanoString data also showed downregulation of endothelial markers such as PECAM1 and VWF, alongside upregulation of the tumor microenvironment and fibrosis-related pathways in HCAECs." (PMID 41296447, 2025). "Injection of purified VWF together with tumor cells could correct the phenotype and show similar metastatic foci in both wild-type and VWF deficient mice." (PMID 39282473, 2024). "Among the non-immune cells, apart from a small population of tumor-associated endothelial cells (21 cells, 0.07% of the total cells, marked with VWF and ENG), the rest were cancer cells (11,228 cells, 35.46% of the total cells, marked with GPC3 and ASS1)." (PMID 38169544, 2024). "Also, hyperglycemia leads to an increase in the Von Willebrand factor in the vascular endothelium promoting tumor cell adhesion and transendothelial tumor cell movement and the development of metastases." (PMID 38835644, 2024). "Further studies revealed that the hub genes MRPL20, COL4A1, and VWF played key roles in tumor energy metabolism, cell adhesion, and angiogenesis, showing the possibility of inhibiting BC cell development and metastasis by regulating these genes and their interactions." (PMID 39529627, 2024). "Interestingly, our data showed that MpEV-EPC showed the upregulation of vWF, SNAIL, VE-Cadherin, FAP, and ALDH, which are tumor endothelial markers associated with breast TEC." (PMID 38515582, 2024). "Some studies have also demonstrated that the inhibition of vWF can reduce tumour metastasis." (PMID 38600601, 2024). "The pro-coagulatory vWF is released from platelet α-granules and from tumor cells." (PMID 39114075, 2024). "Furthermore, vWF, in combination with thrombin, contributes to the formation of tumour-platelet aggregates, enabling tumour cell survival and their successful metastasis." (PMID 38785560, 2024). "The current findings indicated that inhibiting the expression of VWF and overexpressing hsa-miR-1972 significantly affected the malignant tumor markers and angiogenic factors, which could be developed as a novel strategy for treating BC patients." (PMID 39529627, 2024). "VWF may contribute to this process by interacting with tumor cells, endothelial cells, and platelets through various cell membrane receptors, such as platelet glycoprotein (GP)Ibα, P-selectin, ανβ3 and αIIbβ3 integrins, and glycocalyx." (PMID 39282473, 2024). "The combination of anti‐vWF neutralizing antibody with sorafenib further limited PDX tumor growth, showing that the suppression of potent activators of VEGFR and FGFR could be a new strategy to improve the efficacy of sorafenib treatment in HCC." (PMID 37387563, 2023). "Similarly, the deletion of von Willebrand factor (vWF), the major ligand of GPIbα, markedly increased pulmonary metastasis following the injection of tumour cells." (PMID 38106409, 2023).
tumor (continued). "The vascular endothelial growth factor (VEGF) increases the proliferation and differentiation of vascular endothelial cells (the principal producer of VWF) during angiogenesis, which happens during tumor growth, resulting in higher serum VWF levels in cancer patients." (PMID 36991043, 2023). "They discovered that greater metastasis was caused by higher survival of tumor cells in the lung during the first 24 h in the absence of vWF." (PMID 37626742, 2023). "Finally, the presence of vascularization, which is required for IgM accumulation in BXPC3 tumor tissue, was investigated by evaluating the expression of VWF, a typical marker for endothelial cells." (PMID 38017492, 2023). "A total of 3842 endothelial cells from seven tumor samples and one paracancerous tissue were obtained from the GEO database, based on the marker genes VWF, CDH5, RAMP2 and CLDN5,26, 27 of which 3724 and 118 cells were derived from cancer tissues and paracancerous tissue, respectively." (PMID 37726969, 2023). "Blocking GPIba, the part of the GPIb-IX-V receptor complex that binds platelets to VWF, affects the VWF-GPIba interaction and markedly inhibited platelet, tumor cells and endothelial cell interactions and pulmonary metastasis potential in an in vitro and mouse in vivo study of pulmonary metastases." (PMID 35327035, 2022). "In step with VWF having a role in tumor metastasis, ADAMTS13 may also have a supportive role to play here." (PMID 35327035, 2022). "VWF is also postulated to be a mediator of the hematogenous spread of tumors by facilitating the formation of a ‘platelet-taxi’ or by interacting directly with tumor cells to promote metastasis." (PMID 35327035, 2022). "Reduced ADAMTS13 levels may, therefore, increase the chance of tumor metastasis by increasing the availability of large VWF multimers." (PMID 35327035, 2022). "In particular, ALPL, APOL6, SON, and VWF were lowly expressed in tumor tissues." (PMID 35991564, 2022). "Blocking this VWF–platelet interaction results in reduced tumor cell interactions with platelets." (PMID 35327035, 2022). "Building on the theory that VWF may help to create a ‘platelet-taxi’ for tumor cells, it can be envisioned that larger VWF multimers may increase platelet adhesion to cancer cells and further promote metastasis." (PMID 35327035, 2022). "Therefore, whilst helpful in promoting the VWF–tumor–platelet-taxi, it is likely that low ADAMTS13 levels per se are not the sole driver of this phenomenon." (PMID 35327035, 2022). "Some tumor cells acquire the ability to produce VWF to promote metastasis and hide in a shell of VWF and platelets, and even the maturation of osteoclasts is regulated by VWF." (PMID 34572000, 2021). "Therefore, approaching the tumor from the leaky vasculature, platelets first experience and attach to collagen, either via vWF, which via its A3-domain decorates collagen, or directly via collagen receptors." (PMID 33937274, 2021). "The increased concentration of the highly adhesive VWF multimers may modulate platelet-tumour cell interactions along the endothelium, contributing to tumour invasion and metastasis." (PMID 33571850, 2021). "Suppression of t-NETs in tumor-bearing mice by inhibition of PAD4, or release of Amyloid β by BACE inhibition not only suppressed tumor growth but also brought about a decrease in thrombus formation as quantified by levels of clotting factors; vWF and fibrinogen." (PMID 33514748, 2021). "In addition, vWF is a marker of vascular endothelial cells, and it is routinely used to identify vessels in tumor tissues." (PMID 34884420, 2021). "The lack of staining-intensity differences for vWF, cytokeratin, and desmin showed that a reduced vascular supply for the tumours through the chorioallantoic membrane was not the cause of cell death." (PMID 33604316, 2021). "Direct interactions between VWF, tumour cells, platelets and endothelial cells may promote haematogenous dissemination and thus the formation of metastatic foci." (PMID 33571850, 2021).
tumor (continued). "We demonstrate for the first time that the expression of the genes CA9, NDUFA4L2, EGLN3, BHLHE41, IGFBP3, and ANGPTL4, regulated by HIF1, is largely correlated, and along with VWF, the expression levels of these genes during tumor progression decreased coordinately." (PMID 34046336, 2021). "Consequently, the expression of CA9, NDUFA4L2, EGLN3, BHLHE41, VWF, IGFBP3, and ANGPTL4 is associated with ccRCC tumor progression and decreases at stage 4 after initial growth relative to normal tissues." (PMID 34046336, 2021). "This highlighted the high specificity with which VWF induces tumour cell apoptosis." (PMID 33571850, 2021). "Importantly, it has been demonstrated that this highly polymeric VWF has a significantly enhanced functionality evidenced by the ristocetin cofactor and tumour-induced platelet aggregation assays." (PMID 33571850, 2021). "Through VWF, tumor-activated platelets are delivered to the vessel wall." (PMID 34046336, 2021). "As a result, the ER+ cancer sample was clustered with ER+ tumor cells (ESR1+, KRT18+, and KRT5−), KRT5+/EPCAM+ double-positive cells, cancer-associated fibroblasts (CAFs) (DCN+), macrophages (CD68+), KRT5+/EPCAM− cells, and endothelial cells (VWF+)." (PMID 34685653, 2021). "The hypoxic microenvironment of the tumor promotes the malignant cells to dedifferentiate and express endothelial cell markers such as von Willebrand factor (vWf), vascular endothelial-cadherin, CD31, laminin 5 γ2-chain, and EphA2 resulting in the formation of ‘endothelial cell-like cells’." (PMID 34613483, 2021). "The ultra-large VWF is capable of binding to cancer cells and platelets with high affinity, forming heterotypic aggregates that promote the adhesion to vessel walls and the subsequent transmigration of tumour cells across the blood vessel." (PMID 33571850, 2021). "In addition, it has been found that the release of tumour thrombin induces the production of VWF and facilitates the adhesion of cancer cells to the endothelium." (PMID 33571850, 2021). "Besides, α-granules also contain many growth factors, a wide variety of chemokines, MMPs, proteins like thrombospondin, fibrinogen, fibronectin, vitronectin, Von Willebrand factor (VWF), and inflammatory proteins that stimulate tumor growth and angiogenesis." (PMID 33925575, 2021). "VWF has also been demonstrated to protect disseminated tumour cells (DTCs) from chemotherapy." (PMID 33571850, 2021). "Thus, it can be said that TCIPA increases survival of circulating tumor cells due to the presence of integrins and the GP IIb/IIIa receptor on the platelet surface, which via fibrinogen or vWF interact with tumor integrins." (PMID 33146401, 2021). "VWF has been shown to play an important role in tumour progression and metastasis." (PMID 33571850, 2021). "Some tumor cells acquire the ability to produce VWF to further enhance these effects." (PMID 34572000, 2021). "vWF is widely recognized as a marker of endothelial cell activation; however, its role in tumor-associated platelet activation has not been as thoroughly investigated as that of P-selectin." (PMID 32191918, 2020). "In addition, VWF tethers circulating platelets to the endothelium as part of the processes of coagulation, inflammation, and also tumor progression." (PMID 32708334, 2020). "Vascular permeability is induced locally in the proximity of tumor cell-platelet microemboli and might be potentiated by further exposure of subendothelial vWF, TF, and collagen." (PMID 33042789, 2020). "Additionally, tumor cells bind to the platelet adhesive proteins such as fibronectin and von Willebrand factor via integrins to form tumor emboli." (PMID 31579438, 2019). "Interestingly, PAI-1 concentration increased not only in plasma, but also in the lungs, while vWF rose in primary tumours, suggesting a possible different cellular source of these two major regulators of haemostasis: lungs and tumour cells, respectively." (PMID 30683749, 2019).